MIR8052 (microRNA 8052)
Synonyms: hsa-mir-8052
Gene: MicroRNA gene on chromosome 11 (130,666,735 to 130,666,803, forward strand). Ensembl gene ENSG00000274999.
Homologues: Orthologues: chimpanzee MIR8052 (100% identical).